ANKRD54 (ankyrin repeat domain 54)
Description:
Plays an important role in regulating intracellular signaling events associated with erythroid terminal differentiation.
Synonyms: LIAR
Tractability: PROTAC: ubiquitination databases record sites on it.
Gene: Protein-coding gene on chromosome 22 (37,830,853 to 37,849,327, reverse strand). Ensembl gene ENSG00000100124.
Subcellular location: Nucleus; Cytoplasm; Midbody
Subcellular location (Human Protein Atlas): Microtubules; Midbody; Nucleoplasm
Gene Ontology:
Molecular function: protein binding; protein kinase regulator activity; protein-containing complex binding
Biological process: positive regulation of erythrocyte differentiation; regulation of intracellular signal transduction
Cellular component: cytoplasm; midbody; nucleus
Genetic constraint (gnomAD): Loss-of-function variants: 26 observed, 32.03 expected, observed/expected ratio (o/e) 0.81, 90% interval 0.59 to 1.13. The synonymous counts are far from expectation, so gnomAD's model fits this gene poorly and the ratio says little. Missense variants: 384 observed, 357.43 expected, observed/expected ratio (o/e) 1.07, 90% interval 0.99 to 1.17. Synonymous variants: 209 observed, 161.48 expected, observed/expected ratio (o/e) 1.29, 90% interval 1.15 to 1.45.
Homologues: Orthologues: chimpanzee ANKRD54 (99% identical), macaque ANKRD54 (99% identical), dog ANKRD54 (96% identical), pig ANKRD54 (96% identical), guinea pig ANKRD54 (94% identical), rat Ankrd54 (93% identical), mouse Ankrd54 (92% identical), zebrafish ankrd54 (62% identical), tropical clawed frog ankrd54 (59% identical), Drosophila melanogaster wtrw (24% identical), Caenorhabditis elegans trpa-1 (19% identical). Paralogues in human: ANKRD61 (22% identical).
Diseases named in the same sentence as ANKRD54 in open-access papers:
ANKRD54 is named in the same sentence as 3 diseases in open-access papers, as found by Europe PMC text mining. Sharing a sentence is not in itself a finding about the gene and the disease. The quoted sentences say what the papers report.
cancer (1 paper, 2019). A tumor composed of atypical neoplastic, often pleomorphic cells that invade other tissues. "Instead, low lnc-ANKRD54-1:1 expression is associated with the upregulation of important cancer pathways (mostly involved in protein kinase A and cAMP response element-binding protein signaling) and the downregulation of many immune-associated and apoptosis-related pathways." (PMID 31810243, 2019). "Other lncRNAs were mainly correlated with either immune-associated pathways, with lnc-CGRRF1-3:1 as an example, or cancer-associated pathways, with lnc-ACSBG2-1:1 and lnc-ANKRD54-1:1 as examples." (PMID 31810243, 2019). "For lnc-ANKRD54-1:1, which is also downregulated in MIBC, cancer- or immune-associated pathways are not enriched in the same direction." (PMID 31810243, 2019).
tumor (1 paper, 2019). "Eight downregulated lncRNAs—lnc-ACSBG2-1:1; lnc-ANKRD54-1:1; lnc-BOD1-1:7, -1:8, and -1:9; and lnc-MUC22-1:1, -1:7, and -1:8—demonstrated correlation between lower patient survival rate with lower expression of lncRNA, indicating a potential tumor-suppressing role for these lncRNAs." (PMID 31810243, 2019).
ANKRD54 also shares sentences with these, for which no sentence is quoted: infection (2 papers).